MMP7 (matrix metallopeptidase 7)
Diseases named in the same sentence as MMP7 in open-access papers (continued):
Sharing a sentence is not in itself a finding about the gene and the disease.
tumor (continued). "We previously demonstrated an almost ten-fold increase in the OPN (SPP1) transcriptional level in tumor tissue of HsS4D phenotype compared to LsS4D and about a fourfold increase in MMP7, which is implicated in OPN cleavage." (PMID 36338570, 2022). "In a Polish population with CRC, individuals with the G/G variant genotype of MMP-7-181A>G SNP had a higher risk of lymph node involvement and advanced tumor infiltration than patients carrying the A/A genotype." (PMID 34944846, 2021). "We assessed protein or mRNA expression of final targets of the Wnt/β-catenin pathway, such as WISP1, c-MYC, and MMP7, because of their tight association with tumor progression." (PMID 34233687, 2021). "The reported studies have revealed that the MMP-7 expression has been closely associated with tumor invasion and metastasis." (PMID 34421589, 2021). "Several studies suggested that MMP-7 plays a causal role in the development of platinum resistance in different tumor types." (PMID 33396213, 2020). "The mechanism underlying how MMP7 can promote tumour development in other fields has also earned widespread respect." (PMID 31937294, 2020). "Using several genetic Kras-driven PDAC models, it was shown that both tumor size and metastasis were significantly reduced by MMP7 deficiency." (PMID 32325664, 2020). "It was also reported that MMP7 was associated with the acquisition of the chemosensitivity of 5-FU and doxorubicin because of its role in tumour cell escape from Fas-mediated apoptosis." (PMID 31937294, 2020). "We also found that the expression of MMP7 in PDAC tumor cells shows a positive association with the presence of necrosis but a negative association with microvessel density." (PMID 31428151, 2019). "The increased expression of MMP-7 was identified in poorly differentiated tumours and correlated with a higher risk of ocular metastases and a higher degree of local invasion." (PMID 30539028, 2018). "Co-culturing macrophages with tumor cells caused increased expression of MMP-7 and MMP-9 in the tumor cells." (PMID 29731961, 2018). "MMP-7/9/12 (tumor-associated macrophages), MMP-9 (embryonic cells), MMP-11 (adipose cells) and a myriad of MMPs are known to interact with CAFs, while also causing a transition of mature stromal cells to tumor cells." (PMID 29881724, 2018). "IDH2 has been considered a tumor suppressor because its loss was associated with progression of GC via NF-κB-dependent increases in MMP7 activity." (PMID 27941907, 2016). "MMP-7 expression in tumor cells revealed a positive association with more frequent occurrence of necrosis in the main mass of tumor (R = 0.402, p = 0.031) and a negative correlation with the lower index of MVD (R = −0.681, p = 0.000)." (PMID 27429508, 2016). "The anti-tumor effect of fibulin-5 is mediated through tumor microenvironment and suppression of MMP-7, which is overexpressed in NSCLC and associated with poor prognosis." (PMID 25909283, 2015). "Surprisingly, MMP7 loss leads to an increase in colony formation in soft agar but a decrease in tumor formation in nude mice." (PMID 25875355, 2015). "In summary, low expression of KAI1/CD82 combined high expression of CD44, MMP7 and β-catenin was found to be associated with tumor metastasis and poor prognosis in CRC." (PMID 26408312, 2015). "Our work has demonstrated that PKP3 loss leads to an increase in migration, invasion, tumor formation and metastasis and that these functions are dependent upon the increase in MMP7 expression upon PKP3 knockdown." (PMID 25875355, 2015). "The increase in MMP7 levels is required for cell migration and invasion in vitro and tumor formation in nude mice as loss of MMP7 in the PKP3 knockdown cells results in a reversal of these phenotypes." (PMID 25875355, 2015). "MMP-7 is a matrix degrading protein usually associated with tumor invasion and angiogenesis in cancer progression, but has also been linked to induction of proliferation and apoptosis." (PMID 25929687, 2015).
tumor (continued). "Our results suggest that in HCT116 cells, the increase in MMP7 levels is driven by PRL-3 over-expression in the PKP3 knockdown clones and that MMP7 is required for tumor formation in-vivo upon PKP3 loss." (PMID 25875355, 2015). "The underlying mechanism of 5-HT1DR-promoted tumor invasion was through its activation on the Axin1/β-catenin/MMP-7 pathway." (PMID 26214021, 2015). "In gastric carcimona, MMP7 expression was positively associated with tumor size, while negatively associated with PTEN expression." (PMID 24143235, 2013). "Several of those studies link MMP7 with a disrupted Fas-mediated apoptotic response, and inflammation-related facilitation of tumor growth has been proposed to be caused by MMP7 cleavage of Fas ligand." (PMID 21991341, 2011). "The expression level of MMP-7 is significantly associated with the transformation of tumor cells, phenotypes of aggressive cancers and stage of tumor progression, especially in tumors of gastrointestinal tract." (PMID 20939893, 2010). "MMP-7 is unique in its restricted expression in tumor cells, indicating that MMP-7 expression is in a tumor-associated fashion." (PMID 20939893, 2010). "MMP7 has been related to the loss of tumor cell response to cytotoxic agents although the exact mechanism is not fully understood." (PMID 19266094, 2009). "Elevated MMP-7 levels in the blood of patients with EnOC may indicate increased activity of proteolytic processes associated with tumor progression." (PMID 41007705, 2025). "Accordingly, a pan-cancer transcriptomic analysis recently revealed a positive association between MMP7 expression and the infiltration of CAFsand myeloid cells across most tumor types, suggesting a broad involvement of MMP-7 in shaping the stromal and immune landscape." (PMID 41335396, 2025). "In addition to its association with tumor growth, migration, metastasis, and poor prognosis, MMP-7 exerts its oncogenic effects largely through degradation of the ECM, particularly the basement membranes." (PMID 41335396, 2025). "Furthermore, abundant MMP‐7 expression promotes the proliferation, invasion, and migration of tumor cells and was indeed associated with lower survival rates in PDAC patients." (PMID 39263943, 2024). "Furthermore, the tumor invasion-related proteins MMP-7 and MMP-9 were decreased in the context of MMP-12 deficiency." (PMID 38511770, 2024). "Additionally, our findings highlighted the association of ZMIZ1 with key factors involved in tumor progression, such as MMP7, MKP-1, and SSBP2, underscoring its multifaceted impact on TSCC biology." (PMID 38866828, 2024). "Both CD14+APOE+ cells and MMP7+ tumour cells were associated with worse survival." (PMID 39187937, 2024). "In addition to this, in tongue squamous cell carcinoma, the high expression of MMP-7 accelerated in vitro tumor cell growth and migration and increased the risk of nodal metastasis in vivo, while its suppression produced the opposite effect." (PMID 36547091, 2022). "Moreover, SNPs in MMP7 are associated with an increased risk of cancer development, tumor characteristics and the course of disease." (PMID 36009438, 2022). "However, MMP1 rs1799750 and MMP7 rs11568818 were significantly associated with tumor histological grade (p < 0.05)." (PMID 36009438, 2022). "MMP-7 is implicated in multiple processes of tumor development." (PMID 36776395, 2022). "Furthermore, MMP7 expression is strongly associated with pathological stages, clinical outcomes, tumor mutational burden (TMB), and microsatellite instability (TSI)." (PMID 35785154, 2022). "Furthermore, it was reported that increased MMP7-secretion was associated with tumor proliferation, decreased response to chemotherapy, and a poor prognosis in NSCLCs." (PMID 34200100, 2021). "Upregulation in the MMP-7 and -9 expressions are significantly correlated with LN metastasis in association with the higher expression of Ki67, which induces cellular proliferation, promoting tumor invasiveness in early CC cases." (PMID 34912809, 2021).
tumor (continued). "Furthermore, expression of MMP-7 was associated with tumour N stage (P = 0.03) and neural invasion (P = 0.002)." (PMID 33005257, 2020). "Expression of MMP-7 was associated with tumour N stage and neural invasion." (PMID 33005257, 2020). "These promising results and the urgent need for chemotherapy-predictive markers led us to evaluate whether MMP-7 tissue and serum levels are associated with tumor progression and survival in patients with advanced BC treated with platinum-based chemotherapy." (PMID 33396213, 2020). "Although MMP7 involvement in PDAC initiation and progression has been reported, our results showing high MMP7 plasma levels in association with early tumor progression in PDAC‐GEM models and in patients with PDAC at stages IA, IB, and IIA confirm its value as a potential early diagnostic biomarker." (PMID 29941541, 2018). "The overexpression of MMP7 was associated with tumor proliferation, and a poor prognosis in NSCLC." (PMID 30591011, 2018). "It is worth emphasizing that we found a maximum increase in diagnostic sensitivity for the combination of MMP-7 with both tumor markers to 75% in stage I, even to 81%–100% in stages II-IV as compared with the use of either marker alone or of both comparative tumor markers together." (PMID 28662671, 2017). "Thus, the results in this paper suggest that the increased tumor formation observed upon PKP3 loss requires the expression of MMP7." (PMID 25875355, 2015). "Since this result was in contrast to the results obtained in the migration and invasion assays, we determined whether MMP7 loss leads to an alteration in tumor formation in vivo." (PMID 25875355, 2015). "ADAM9 and MMP7 are involved in cell-cell and cell-matrix interaction, are able to cleave and release a number of molecules with important role in tumorigenesis, resulting causally involved in tumor formation and progression." (PMID 23437250, 2013). "MMP-7 is a matrix metalloprotease that has been associated with tumour invasion and metastasis." (PMID 18212756, 2008). "More detailed exploration is required to determine whether rs1943779 alters expression of MMP7, how this affects tumour invasiveness and whether other closely linked variants are involved." (PMID 19094228, 2008). "Simultaneously, activation of oncogene encoding β-catenin could stimulate the downstream target, MMP-7, to suppress tumor cell apoptosis and degradation of basic membrane." (PMID 18681964, 2008). "Furthermore, the expression of proteins associated with tumor cell metastasis, including MMP7, MMP9, N-cadherin, vimentin and Snail, was significantly reduced, and the corresponding expression of proteins related to tumor cell apoptosis, such as caspase-3, PPAR and GSK-3β, was strongly increased." (PMID 35348430, 2022). "For example, the outcome estimations based on MMP7, a gene which encodes for an enzyme that degrades extracellular proteins, were discordant before and after macrodissection, most likely because RNA expression of MMP7 is higher in stroma compared to tumor cells." (PMID 30342538, 2018). "The clinicopathological data analysis in the same studies was meant to assess whether it is consistent with survival data; in support, it was shown that MMP7 level is significantly associated with aggressive tumor characteristics such as invasion depth, TNM stage, and distant metastasis." (PMID 25919283, 2014). "In this context, researchers designed a ‘masked’ NLS peptide that is only activated in the presence of overexpressed matrix metalloproteinase-7 (MMP-7) in the tumor microenvironment." (PMID 41427517, 2026). "RSPO4 also induced significant suppression of the transcriptional activities of critical Wnt/β-catenin target genes CCND1, c-MYC and MMP7, which play important roles in tumor cell metastasis." (PMID 41522353, 2026). "Tumor cells promote invasion by upregulating matrix metalloproteinases (MMPs), including MMP7 and MMP13." (PMID 40168262, 2025).
tumor (continued). "The subsequent upregulation of MMP-7, driven by AP-1, enhances the metastatic and invasive capabilities of tumor cells." (PMID 41400642, 2025). "Knockdown of MELK results in reducing tumor cell invasion and migration, likely by diminishing the levels of matrix metalloproteinase 7 (MMP7), N-catenin, twist family BHLH transcription factor 1 (Twist1), and snail family transcriptional repressor 2 (Snai2)." (PMID 41291696, 2025). "Three genes (PRSS21, FOXQ1, and MMP7) formed a highly upregulated cluster, with a fold increase greater than 220 in tumor tissues." (PMID 41465326, 2025). "Calcitriol inhibited key tumor progression processes, such as cell proliferation and migration, and downregulated MMP7 and MMP13 mRNAs." (PMID 40168262, 2025). "Interleukin-7 (IL-7), acting via the IL-7 receptor (IL-7R), plays a significant role in tumor progression, is closely associated with a poor prognosis for patients with PC, and is associated with MMP-3 and MMP-7 expression." (PMID 40001606, 2025). "Tumor regions expressing CDKN2A exhibit distinct infiltration of SPP1(+) tumor-associated macrophages (TAMs), MMP7 enrichment, and unique signaling interactions with adjacent regions." (PMID 40406488, 2025). "For instance, MMP-13 promotes invasion at the tumor margins, while MMP-7 activates growth factors to drive proliferation." (PMID 40868818, 2025). "MMP-7 can promote normal cell proliferation and induce cancer cell aggregation, thereby participating in tumor occurrence and metastasis." (PMID 41444284, 2025). "Three genes: PRSS21, FOXQ1, and MMP7, formed a highly upregulated cluster exhibiting a fold increase greater than 220-fold in tumor tissues (Median (Range) = 1273 (228–1598) fold increase)." (PMID 41465326, 2025). "MMP-7 is an enzyme responsible for the degradation of extracellular matrix components, including collagen, laminin, and elastin, which facilitates tumor invasion and metastasis." (PMID 41007705, 2025). "Western Blotting also demonstrated an increased expression of MMP7/MMP9 in TNBC tumor tissues of obese mouse in the HFD group." (PMID 40841364, 2025). "In CC, MMP7 is frequently overexpressed, with higher levels correlating with increased tumor invasion, lymph node metastasis, and poor clinical outcomes." (PMID 40599331, 2025). "IL-8 and mTOR counter oxidative stress by inhibiting GSK-3β, while IL-17 stimulates matrix metalloproteinase 7 (MMP7) expression, driving tumor progression through epithelial-mesenchymal transition." (PMID 40430079, 2025). "In future work, we plan to extend our research by incorporating animal models to experimentally validate the interactions between CD14+APOE+ cells and MMP7+ tumour cells." (PMID 39187937, 2024). "The expression of MMP7 in tumour cells and APOE in myeloid cells was higher in non‐responder (NR) patients compared to responders (R)." (PMID 39187937, 2024). "We observed that CD14+APOE+ cells were prominently represented in samples with immune exclusion, exhibiting a strong correlation with MMP7+ tumour cells." (PMID 39187937, 2024). "Subsequently, we assessed the capacity of tumour cells expressing MMP7 and CD14+ cells expressing APOE to forecast the effectiveness of treatment in patients undergoing immunotherapy." (PMID 39187937, 2024). "This refined analysis confirms that MMP7+ tumour cells exhibit distinct communication patterns with immune cells, particularly through the MIF signalling pathway." (PMID 39187937, 2024). "The cell‒cell communication between MMP7+ tumour cells and CD14+APOE+ cells was consistent with the results based on the ST data." (PMID 39187937, 2024). "Second, while our spatial analysis revealed the co‐location of CD14+APOE+ cells with MMP7+ tumour cells, the functional implications of this co‐localisation were inferred based on known roles of these cell types and their expression profiles." (PMID 39187937, 2024).
tumor (continued). "This study identified immune exclusion and activation patterns in NSCLC and the co‐location of CD14+APOE+ cells and MMP7+ tumour cells as contributors to immune resistance." (PMID 39187937, 2024). "In an immunotherapy cohort from the ORIENT‐3 clinical trial, NSCLC patients who responded unfavourably exhibited higher infiltration of CD14+APOE+ cells and MMP7+ tumour cells." (PMID 39187937, 2024). "Specifically, we selected five ROIs with high MMP7+ tumour cells and five ROIs with low MMP7+ tumour cells in each sample." (PMID 39187937, 2024). "By intersecting these three gene lists, we have identified MMP7 as meeting the criteria and exhibiting the highest level of expression in tumour sites characterised by immune exclusion." (PMID 39187937, 2024). "MMP7 has a role in facilitating tumour growth by stimulating ECM degradation, migration and invasion of tumour cells, and angiogenesis." (PMID 39187937, 2024). "We found that an endothelial program is active in a subset of BTC malignant cells, which also uniquely express high levels of MMP7, a mediator of tumor invasion and metastasis, and exhibited high cell cycling activity." (PMID 39417106, 2024). "Kinesin-8 family: KIF18A affected Akt/MMP7/9 signaling with an impact on tumor invasion and migration and CyclinB1-related signaling with an influence on proliferation." (PMID 38433242, 2024). "The spatial co‐location of CD14+APOE+ cells and MMP7+ tumour cells was observed in ST data and further validated through multiplex immunofluorescence analysis conducted on 20 NSCLC samples." (PMID 39187937, 2024). "The co‐location of CD14+APOE+ cells and MMP7+ tumour cells was observed in both ST and bulk transcriptomics data, validated by multiplex immunofluorescence performed on 20 NSCLC samples." (PMID 39187937, 2024). "Previous studies have demonstrated the action of MMP7 on the development of apoptosis resistance, tumor growth, angiogenesis, and cancer cell invasion." (PMID 38638796, 2024). "Tumor regions expressing CDKN2A exhibit distinctive SPP1+ tumor-associated macrophage (TAM) infiltration and MMP7 enrichment, along with unique signaling crosstalk with adjacent areas." (PMID 38888512, 2024). "Studies have shown that the expression of MMP7 was increased in tumor patients and was related to the depth of tumor invasion, size and number of lymph node metastases." (PMID 38866828, 2024). "In immune exclusion samples, MMP7 showed notable expression within tumour areas, while in samples with immune activation, MMP7 displayed significantly lower expression levels." (PMID 39187937, 2024). "This additional analysis demonstrates similar communication patterns between MMP7+ tumour cells and immune cells, confirming that this phenomenon is not patient specific but rather a broader characteristic of immune exclusion in NSCLC." (PMID 39187937, 2024). "Experimental validation, such as functional assays or in vivo models, is required to definitively establish the mechanistic interactions between CD14+APOE+ cells and MMP7+ tumour cells in promoting immunotherapy resistance." (PMID 39187937, 2024). "We validated the results in the ScRNAseq cohort and detected the upregulation of MMP7 in CDKN2A-positive tumor cells." (PMID 38888512, 2024). "First, further validation in independent cohorts and prospective studies is necessary to confirm clinical utility of CD14+APOE+ cells and MMP7+ tumour cells." (PMID 39187937, 2024). "COL17A1, ITGA10 and MMP7 showed high intertumoral heterogeneity between tumor tissues and adjacent tissues." (PMID 36936416, 2023). "Tumor‐associated marker expression was significantly different among all cell types for MMP2, MMP7, MMP9, MMP12, ABHD5, ADAMTS1, AP‐1, and MGLL each with p < 0.001." (PMID 38037545, 2023). "By real-time RT-PCR analysis, the expression of Mmp-7 was significantly higher in the tumor of S100a4-Cre; Ext1f/f mice." (PMID 36809261, 2023).